BCAT1 (branched chain amino acid transaminase 1)
Diseases named in the same sentence as BCAT1 in open-access papers (continued):
Sharing a sentence is not in itself a finding about the gene and the disease.
lung cancer (continued). "Several studies have indicated that BCAT1 overexpression is linked to multi-drug resistance, such as decreased chemosensitivity to CDDP in prostate cancer, and loss of BCAT1 overcoming resistance to EGFR tyrosine kinase inhibitors in lung cancer." (PMID 39075053, 2024). "Moreover, we identified WQQ-345 as a novel BCAT1 inhibitor exhibiting antitumor activity both in vitro and in vivo against TKI-resistant lung cancer with high BCAT1 expression." (PMID 39143065, 2024). "Previous studies have shown that increased BCAT1 transcription is associated with α-KG depletion and high expression of SOX2, promoting bone metastasis of lung cancer cells, while knockdown of BCAT1 could reduce cell migration in vitro and metastasis in vivo." (PMID 36998464, 2023). "Furthermore, we demonstrated that knocking down BCAT1 reduces SOX2 expression in another metastatic lung cancer cell line H661." (PMID 34646394, 2021). "Taken together, our data indicates that BCAT1 plays an important role in driving lung cancer cell metastasis through modulating the expression of stemness factor SOX2 at the post-transcriptional level, and identify α-KG as a key signaling intermediate in this process." (PMID 34646394, 2021). "Furthermore, combination studies to test potential synergistic effects among BCAT1 and other lung cancer biomarkers, such as SHOX2, PTEGR4, could also be considered." (PMID 36123616, 2022). "WQQ-345, a novel BCAT1 inhibitor, has demonstrated antitumor activity in both in vitro and in vivo models of TKI-resistant lung cancer with high BCAT1 expression." (PMID 40438606, 2025). "High levels of BCAT1 promote the expression of SRY-box 2 (SOX2) by reducing alpha-ketoglutarate (α-KG), leading to the migration and metastasis of lung cancer cells." (PMID 40438606, 2025). "BCAT1 can enhance BCAA metabolism, thereby increasing mitochondrial respiration and biosynthesis, reducing reactive oxygen species (ROS) levels, and ultimately enhancing NF-κB pathway signaling, promoting lung cancer development." (PMID 40438606, 2025). "BCAT1 expression levels were markedly elevated in lung cancer tumors compared with adjacent noncancerous tissues." (PMID 39143065, 2024). "In addition, our studies define a new pathway that involves α-KG as a key metabolic signaling intermediate between BCAT1 and the post-transcriptional regulation of SOX2 expression in metastatic lung cancer cells." (PMID 34646394, 2021). "Increased expression of both BCAT1 and SOX2 were also observed in H661 cells which originated from lymph node metastasis of a patient with large cell carcinoma, compared to another primary lung cancer cell line H441." (PMID 34646394, 2021). "Our earlier research identified WQQ-345 as a novel BCAT1 inhibitor featuring a unique bridged bicyclic skeleton and demonstrating both in vitro and in vivo antitumor activity against tyrosine kinase inhibitor (TKI)-resistant lung cancer with high BCAT1 expression." (PMID 40005214, 2025).
ovarian carcinoma (19 papers, 2012 to 2025). A malignant neoplasm originating from the surface ovarian epithelium. "BCAT1 overexpression has been shown to be associated with several cancers including glioblastoma, nasopharyngeal carcinoma, ovarian cancer and hepatocellular carcinoma." (PMID 31226958, 2019). "Nevertheless, BCAT1 may serve as a more reliable diagnostic and prognostic marker for ovarian cancer." (PMID 40687583, 2025). "Interestingly, knockdown of BCAT1 was associated with reduced migration of nasopharyngeal and ovarian cancer cells." (PMID 31428460, 2019). "Studies have shown that BCAT1 levels are markedly elevated in the blood and ovarian tumour tissues of ovarian cancer patients and that its overexpression in tumour tissues is closely associated with chemotherapy resistance." (PMID 40687583, 2025). "Elevated BCAA catabolism in ovarian cancer is substantiated by previous studies demonstrating increased expression of the BCAA catabolic enzyme BCAT1 in HGSOC." (PMID 40066850, 2025). "In a related study in ovarian cancer, BCAT1 was significantly hypermethylated in low malignant potential (LMP) and high grade (HG) plasmacytoid epithelial ovarian tumors." (PMID 39324007, 2024). "An investigation on ovarian cancer cells showed that suppressing BCAT1 can downregulate involved genes in tumorigenesis and reduce ATP levels generated by the TCA cycle." (PMID 37637065, 2023). "Silencing BCAT1 in ovarian cancer cells results in decreased proliferation, invasion, and migration and correlates with prolonged survival time in xenograft models." (PMID 36195845, 2022). "Other than hypomethylation, BCAT1 was identified as somatically amplified and overexpressed in ovarian cancer cell lines with high invasive and migratory ability." (PMID 33488950, 2020). "Silencing of BCAT1 arrested cells at S phase, significantly affected cell proliferation, colony formation, migration, invasive ability of ovarian cancer cells." (PMID 33488950, 2020). "In ovarian cancer, BCAT1 was first reported to be up-regulated in chemoresistant epithelial ovarian tumors, however, the mechanism of drug resistance was not identified." (PMID 33488950, 2020). "Knockdown of the BCAT1 expression in epithelial ovarian cancer (EOC) cells led to sharp decrease of cell proliferation, migration and invasion and inhibited cell cycle progression." (PMID 26372729, 2015). "Additionally, inhibiting BCAT1 expression in ovarian cancer can reduce amino acid levels and significantly suppress tumour progression both in vitro and in vivo." (PMID 40687583, 2025). "Upregulation of BCAT1 is also reported in other human malignancies, such as ovarian cancer." (PMID 37637065, 2023). "BCAT1 has been shown to play a key role in promoting tumor cell invasion and migration in a variety of solid tumor malignancies including hepatocellular carcinoma, non-small cell lung cancer as well as ovarian cancer." (PMID 36195845, 2022). "As observed in other tumor types, BCAT1 was shown to be regulated by c-Myc in ovarian cancer cells." (PMID 33488950, 2020). "Silencing of BCAT1 inhibits the tumorigenesis of ovarian cancer." (PMID 32855634, 2020). "BCAT1 has also been found hypo-methylated in other cancer types such as ovarian cancer." (PMID 28947923, 2017). "Additionally, survival was prolonged when BCAT1 was suppressed in a xenograft model of advanced epithelial ovarian cancer." (PMID 28122348, 2017). "On the other hand, an inverse relationship between BCAT1 and IDH1/2 was found in epithelial ovarian cancer (EOC), where BCAT1 silencing suppressed the expression of IDH1/2 genes." (PMID 29211698, 2018). "Considering their role in TCA cycle, the metabolic link between BCAT1 and IDH1/2 may contribute to elevated cellular migration and invasion in ovarian cancer." (PMID 32238881, 2020). "Interestingly, in 2015, an inverse relationship between BCAT1 and IDH1/2 was found in epithelial ovarian cancer, where BCAT1 knockdown inhibited the expression of IDH1/2." (PMID 32238881, 2020).
ovarian carcinoma (continued). "However, when mice were injected with SKOV3 ovarian carcinoma cells with suppressed BCAT1 expression, tumor burden was not alleviated, although survival rates were significantly increased as compared with control animals." (PMID 29211698, 2018). "This suggests that BCAT1 may be a direct transcriptional target of c-MYC and an effector through which c-MYC exerts its oncogenic influence, a relationship that has previously been demonstrated in nasopharyngeal carcinoma, but needs to be explored in ovarian cancers." (PMID 25572314, 2015).
hepatocellular carcinoma (18 papers, 2018 to 2025). A malignant tumor that arises from hepatocytes. "Other investigators have reported increased BCAT1 expression and decreased BCAT1 promoter methylation levels in most hepatocellular carcinomas." (PMID 39324007, 2024). "In hepatocellular carcinoma, knockdown of BCAT1 or administration of leucine activated mTOR signaling, inhibited autophagy, and increased cisplatin sensitivity and percentage of cell apoptosis." (PMID 36163180, 2022). "In hepatocellular carcinoma, methylation of the BCAT1 promoter is decreased, resulting in higher BCAT1 expression." (PMID 36358687, 2022). "Consistent with this, overexpression of BCAT1 in hepatocellular carcinoma leads to chemoresistance following cisplatin treatment." (PMID 34354601, 2021). "BCAT1 takes part in the progression of several malignancies, including glioblastoma, hepatocellular carcinoma, and nasopharyngeal carcinoma." (PMID 32855634, 2020). "BCAT1 accelerates the proliferation of hepatocellular carcinoma cells." (PMID 32855634, 2020). "And investigators studying adverse outcomes in non-alcoholic fatty liver disease showed that high BCAT1 expression and hypomethylation predicted an increased incidence of adverse outcomes such as hepatocellular carcinoma (HCC)." (PMID 39324007, 2024). "Interestingly, in Hepatocellular carcinoma (HCC), only the levels of BCAT1/2 are upregulated, leading to chemoresistance, while BCKDH and other enzymes involved in BCAA catabolism are decreased." (PMID 37637065, 2023). "Moreover, the levels of BCAT1/2 are upregulated, while BCKDH is decreased, in hepatocellular carcinoma." (PMID 40723225, 2025). "In addition, the expression of the BCAA degradation pathway in extrahepatic cholangiocarcinoma and gallbladder cancer was similar to the expression in ICC, and in hepatocellular carcinoma (HCC), both BCAT1 and BCAT2 were highly expressed in tumour samples as previously reported." (PMID 37076565, 2023).
chronic myeloid leukemia (16 papers, 2018 to 2025). "Interestingly, a BCAT1 overexpression plays a significant role also in the pathogenetic mechanisms underlying blast crisis in chronic myeloid leukemia." (PMID 30813354, 2019). "One recent study suggests that the highly-expressed BCAT1 in blast crisis chronic myeloid leukemia (BC-CML) re-amidate BCKA into BCAA, thus promoting the mTOR signaling pathway and the progress of BC-CML." (PMID 35785192, 2022). "Musashi2 (MSI2) was shown to bind to MSI binding sites in the 3′ untranslated region of BCAT1 in human chronic myeloid leukemia cell lines and positively regulate BCAT1 transcription." (PMID 36358687, 2022). "Most recently, a new posttranscriptional regulator of BCAT1 expression was identified in chronic myeloid leukemia (CML), the musashi RNA binding protein 2 (MSI2) [18▪▪]." (PMID 29211698, 2018). "Notably, BCAT1 promotes BCAA production in BCR-ABL driven chronic myelogenous leukemia, in which BCAT1 blockade impairs B-cell proliferation and causes differentiation." (PMID 38854072, 2024). "In chronic myeloid leukaemia (CML), increased BCAT1 expression has been shown to elevate intracellular BCAA levels and activate the mTORC pathway)." (PMID 40839139, 2025). "In chronic myeloid leukaemia (CML), BCAT1 promotes clonal growth by forming BCAAs from amino groups of BCKAs." (PMID 38028625, 2023). "In chronic myeloid leukemia (CML), BCAT1 promotes the clonogenic growth by the reamination of BCKAs to form BCAAs and, thus, activating the mTOR pathway." (PMID 35409380, 2022). "Although the BCAT1::BAALC fusion has not been previously reported, both BCAT1 and BAALC are associated with chronic myeloid leukemia." (PMID 40242470, 2025).
myeloid leukemia (14 papers, 2018 to 2025). A clonal proliferation of myeloid cells and their precursors in the bone marrow, peripheral blood, and spleen. "Consistently, individuals diagnosed with IDHWT/TET2WT myeloid leukemia, α-KG is maintained at normal levels and therefore BCAT1 expression is promoted compared to IDHmut/TETmut myeloid leukemia." (PMID 38218942, 2024). "It has been reported that EZH2 inactivation and oncogenic NRAS mutations together activate BCAT1, enhance BCAA metabolism and mTOR signaling, and promote the development of myeloid leukemia." (PMID 39324007, 2024). "Because BCAT1's effects appear to be LSC-specific and gabapentin is commonly accessible and suitable for clinical application, it is fascinating to observe if clinical ways to utilize BCAT1 as a targeted therapy in myeloid leukemias are being developed." (PMID 37735675, 2023). "The cytosolic branched-chain aminotransferase (BCAT1) has received attention for its role in myeloid leukaemia development, where studies indicate metabolic adaptations due to BCAT1 up-regulation." (PMID 35453368, 2022). "For example, BCAT1 enhances branched-chain amino acid production and promotes myeloid leukemia progression." (PMID 33517886, 2021). "For patients with IDH (WT)/TET2 (WT) myeloid leukemia, a high level of BCAT1 is a strong predictor of worse survival outcomes, and the BCAT1 level significantly increases on disease relapse." (PMID 33511116, 2020). "However, we recently demonstrated that BCKA transamination by the BCAT1 enzyme builds up the BCAA pool in myeloid leukemia (ML) cells, essentially running in the reverse direction." (PMID 31114791, 2019). "Bcat1 expression is upregulated in blast phase CML and AML and increased Bcat1 contributes to myeloid leukemia progression." (PMID 36100596, 2022). "Research has found that BCAT1 is abnormally activated in chronic myeloid leukemia (CML) in both humans and mice, promoting BCAAs production via the MSI2-BCAT1 axis, thereby driving the development of myeloid leukemia." (PMID 40438606, 2025). "The BCAT1-CXC motif may help buffer ROS levels within AML cells, influencing cell proliferation, which could impact the ROS-mediated development of myeloid leukemia." (PMID 40438606, 2025). "Altogether, this study provides the first evidence to suggest that the BCAT1 CXXC motif may contribute to the buffering of ROS levels inside AML cells, which may impact ROS-mediated processes in the development of myeloid leukaemia." (PMID 35453368, 2022). "Furthermore, WT BCAT1 cells were more resistant to apoptosis compared with CXXS BCAT1 cells, an important observation given the role of ROS in apoptotic signalling and myeloid leukaemia development." (PMID 35453368, 2022). "Since the effects of BCAT1 seem LSC-specific and given that gabapentin is readily available for clinical use, it will be interesting to see whether clinical strategies are being developed to exploit BCAT1 as a therapeutic target in myeloid leukemias." (PMID 31370337, 2019).
gastric cancer (13 papers, 2020 to 2025). A primary or metastatic malignant neoplasm involving the stomach. "BCAT1-mediated mTOR activation is involved in the lethal biological behaviors of gastric cancer and cervical cancer." (PMID 40438606, 2025). "In gastric cancer, BCAT1 acts as an oncogene by activating the PI3K/AKT/mTOR signaling pathway to promote proliferation, invasion, and angiogenesis." (PMID 39324007, 2024). "Activation of the PI3K/Akt/mTOR pathway by BCAT1 may also promote the proliferation, invasion, and angiogenesis of gastric cancer cells." (PMID 38309289, 2024). "BCAT1 could promote gastric cancer cell invasion, proliferation, and angiogenesis through PI3K/AKT/mTOR signaling pathway." (PMID 37460470, 2023). "Meanwhile, another study showed that miR-98-5p could reduce gastric cancer cell stemness and paclitaxel chemosensitivity by targeting BCAT1." (PMID 35266852, 2022). "Thus, BCAT1 showed a promising target for optimizing antiangiogenesis treatments in gastric cancer." (PMID 39409942, 2024). "Another recent study found that BCAT1 was able to activate PI3K/Akt/mTOR signalling pathway, contributing to the angiogenesis and tumorigenicity of gastric cancer cells, although we did not observe repression of Akt phosphorylation by knockdown of BCAT1 in SCLC cells." (PMID 35318805, 2022).
nasopharyngeal carcinoma (10 papers, 2012 to 2025). A carcinoma arising from the nasopharyngeal epithelium. "The promoter encoding BCAT1 can interact with RNA-binding motif proteins, promoting tumorigenesis in nasopharyngeal carcinoma." (PMID 40438606, 2025). "Depletion of BCAT1 by RNA interference in nasopharyngeal cancer cells effectively blocked the proliferation of cells suggesting a role for BCAT1 in tumorigenesis." (PMID 22355333, 2012). "In addition, the mechanism of BCAT1 and c-Myc gene co-regulating the proliferation and invasion of cancer cells was also found in nasopharyngeal carcinoma (NPC)." (PMID 36119495, 2022). "For instance, knockdown of BCAT1 has an anticancer effect on nasopharyngeal carcinoma." (PMID 32855634, 2020). "BCAT1 was found to induce cell proliferation, migration and invasion in nasopharyngeal carcinoma." (PMID 25869207, 2015). "Previously, we elucidated the function of flotilin-2 (FLOT2) and branched-chain amino acid transaminase 1(BCAT1) in nasopharyngeal carcinoma (NPC)." (PMID 33744853, 2021).
melanoma (9 papers, 2008 to 2025). A malignant, usually aggressive tumor composed of atypical, neoplastic melanocytes. "Interestingly, a study last year reported that knockdown of BCAT1 suppressed melanoma cell proliferation and migration, which was associated with reduced oxidative phosphorylation." (PMID 35318805, 2022). "Branched-chain amino acid transaminase 1 (BCAT1) expression is markedly elevated in melanoma cells, which mediates the metastasis of specific nitrogen atoms in branched-chain amino acids, and inhibition of BCAT1 suppresses tumor proliferation." (PMID 40539068, 2025). "The inhibition of the proliferation and migration of melanoma cells was observed in BCAT1 knockdown." (PMID 40723225, 2025). "Nonetheless, analysis of samples from patients with malignant melanoma and mouse malignant B16 melanoma cell lines showed that BCAT1 was overexpressed in both sample types." (PMID 37637065, 2023). "The expression of BCAT1 is prominently upregulated in melanoma cells, and the knockdown of BCAT1 suppresses tumor growth through the suppression of oxidative phosphorylation." (PMID 36003368, 2022). "As is similar to other types of cancers, the expression of BCAT1 is significantly upregulated in melanoma." (PMID 34924562, 2021). "Moreover, BCAT1 was overexpressed in malignant melanoma patients and mouse malignant melanoma cells." (PMID 40723225, 2025). "Moreover, BCAT1 knockdown inhibited the proliferation and migration of melanoma cells and decreased oxidative phosphorylation." (PMID 37637065, 2023).
non-small cell lung carcinoma (7 papers, 2018 to 2023). A group of at least three distinct histological types of lung cancer, including non-small cell squamous cell carcinoma, adenocarcinoma, and large cell carcinoma. "BCAT1 is overexpressed in human non-small cell lung cancer, and BCAT1 promotes cell proliferation and invasion by regulating the Wnt signaling pathway." (PMID 38028625, 2023). "BCAT1 is commonly up-regulated in many different cancer lines, such as human glioblastoma, breast cancer, and non-small cell lung carcinoma (NSCLC), while BCAT2 seems more important for pancreatic cancer." (PMID 33669382, 2021).